LINC02871 (long independently transcribed non-coding RNA 2871)
Synonyms: dJ727I10.1; formerly C20orf187
Gene: Long non-coding RNA gene on chromosome 20 (10,986,593 to 11,029,455, forward strand). Ensembl gene ENSG00000125899.
Diseases named in the same sentence as LINC02871 in open-access papers:
LINC02871 is named in the same sentence as 3 diseases in open-access papers, as found by Europe PMC text mining. Sharing a sentence is not in itself a finding about the gene and the disease.
LINC02871 shares sentences with these, for which no sentence is quoted: autoimmune conditions (1 paper); multiple sclerosis (1); rheumatoid arthritis (1).